EZR (ezrin)
Diseases named in the same sentence as EZR in open-access papers (continued):
Sharing a sentence is not in itself a finding about the gene and the disease.
breast carcinoma (continued). "KCNK1 expression was positively correlated with that of LDHA, Pan Kla, ZWINT, ECT2, ANLN, and EZR, reconfirming that KCNK1 played an important role in the proliferation and metastasis of breast cancer." (PMID 38905316, 2024). "Key work from the Roskelley and McNagny laboratories indicated that in breast cancer cells, PODXL drives an Ezrin-dependent collective migration and tumor-budding phenotype." (PMID 36735782, 2023). "Initially characterized in human breast cancer cells, PACE-1 binds to the C-terminal domain of Ezrin and colocalizes with Ezrin in the lamellipodia." (PMID 37371090, 2023). "Ezrin binds to the GEF of Cdc42 to activate the downstream pathway of Cdc42 and promote the directed migration of breast cancer cells." (PMID 37328063, 2023). "The systemic inhibition of ezrin by NSC668394 suppresses the migration and metastasis of breast cancer cells at the distal axillary lymph node and lungs." (PMID 35328667, 2022). "On the other hand, MST4 activated Ezrin-AKT signaling leads to the phosphorylation of BAD which in turn increases the survival and chemoresistance of breast cancer cells." (PMID 36552828, 2022). "It should be noted that ezrin expression is up-regulated and correlates with HER2 expression in human HER2-positive breast cancer cell lines and invasive breast cancers from human patients." (PMID 35328667, 2022). "In the current study, we first investigated the relationship between Ezrin and AJAP1 expression and then evaluated their prognosis accuracy in predicting prognosis of breast cancer patients." (PMID 35311087, 2022). "EZR knockdown significantly inhibited cell proliferation, invasion, chemoresistance and EMT in breast cancer." (PMID 37304008, 2022). "Ezrin and AJAP1 expressions were detected in 377 samples of breast cancer by immunohistochemistry, and different expression patterns between AJAP1 and Ezrin with clinicopathological parameters were analyzed." (PMID 35311087, 2022). "Our observations point to ezrin as the predominant ERM protein responsible for modulating sensitivity to anthracycline and taxane treatment in breast cancer cells." (PMID 36923551, 2022). "In breast cancer cells, whereas CD44 and ezrin localize in different membrane regions at resting state, CD44 association with rafts decreases and its interaction with ezrin increases after induction of migration." (PMID 36439249, 2022). "Previous studies reported that Ezrin promotes migration, invasion and cancer progression in vitro and in vivo, by interacting with AKT thereby regulating the AKT pathway in breast cancer." (PMID 33003361, 2020). "Recent studies showed that ezrin and its interaction partner ACAP4 acetylation is involved in breast cancer metastasis in response to cytokine CCL18 stimulation." (PMID 32647287, 2020). "One unique protein within LKB1 pathway is Ezrin (EZR), which has been shown to mediate breast cancer cell migration, hence facilitating metastasis." (PMID 31191821, 2019). "We observed polarisation of ezrin and CD44 in cells from pleural effusion (PE) or ascitic effusion (AE) of pancreatic and breast cancer patients showing that sc polarity occurs in human patients." (PMID 29491397, 2018). "In addition, it led to new biological findings concerning molecular paths in breast cancer cells linking the tyrosine kinase Syk and two targets involved in cell adhesion and motility: (i) the signaling axis Syk-Src-cortactin and (ii) the direct action of Syk on ezrin." (PMID 28306714, 2017). "Our previous studies in Dx-EVs showed a selective packaging of Ezrin, Radixin, Moesin and CD44 in resistant breast cancer cell-derived EVs." (PMID 26938523, 2016). "In 3D matrigel matrix, perturbation of ezrin activity with small hairpin RNA technology reduced the metastatic and invasive capabilities of MDA-MB-231 and MCF10A breast cancer cell lines." (PMID 26983550, 2016).
breast carcinoma (continued). "We used siRNA silencing of Ezrin, Radixin, Moesin and CD44 to evaluate the role of each protein in regulating P-gp function in drug-resistant breast cancer cells." (PMID 26938523, 2016). "Immunoblotting analysis provided a link between ezrin expression and a key angio/lymphangiogenesis signaling pathway by revealing that ezrin regulates Stat3 activation, VEGF-A/-C and IL-6 expression in breast cancer cell lines." (PMID 25231728, 2014). "The membrane cytoskeletal crosslinker, ezrin, a member of the ERM family of proteins, is frequently over-expressed in human breast cancers, and is required for motility and invasion of epithelial cells." (PMID 22397367, 2012). "Therefore, a positive feedback loop might exist between c-Src/PI3K and ezrin in breast cancer." (PMID 21818323, 2011). "The ezrin gene set also contains ARF1, which is reported to modulate migration and proliferation in breast cancer cell lines via the regulation of the PI3K pathway." (PMID 20731868, 2010). "Moreover, an increased PRA/PRB ratio in breast cancer cells has been shown to induce changes in cell morphology and the loss of cell adhesion in response to progesterone receptor agonists, along with a membrane-to-cytoplasm redistribution of the ERM protein, ezrin." (PMID 18665217, 2008). "By the time we observe lumen filling lesions, or in HER2-overexpressing breast cancer cells, basolateral polarization is lost and HER2, Ezrin, NHERF1, HSP90, and Erbin all join together to form stable signaling complexes that localize within protruding membrane domains." (PMID 40390040, 2025). "Erbin co-localized with HER2, NHERF1, and Ezrin at the plasma membrane and especially within membrane protrusions, which we have previously documented to be an important location of active HER2 signaling in breast cancer cells." (PMID 40390040, 2025). "Among the downstream target genes regulated by KCNK1, ANLN and EZR are involved in cytoskeleton assembly, cell adhesion, and motility, so atomic force microscopy (AFM) was employed to assess the biophysical properties of breast cancer cells." (PMID 38905316, 2024). "The enhanced expression of ezrin promoted proliferation, invasion and EMT of ovarian cancer cells and contributed to aggressive tumour characteristics and poor prognosis of breast cancer." (PMID 36156321, 2023). "Furthermore, the inhibition of Ezrin by NSC668394 can reduce the metastatic burden at the distal axillary lymph node and lungs in breast cancer." (PMID 37371090, 2023). "A similar finding in breast cancer showed that high Ezrin and low E-cadherin expression were more related to lymph node metastasis and poor prognosis." (PMID 37371090, 2023). "Ezrin’s presence in cellular protrusion has been evidenced in transfected MCF7 and observed by immunoelectron microscopy as well as in keratinocytes and breast cancer cells using immunofluorescence." (PMID 36899847, 2023). "Additionally, Ezrin can interact with AKT, which is required for AKT activation to promote breast cancer metastasis." (PMID 34485151, 2021). "Mouse mammary carcinoma cell line overexpressing the non-phosphorylatable form of ezrin, inhibited tumor invasion in vitro." (PMID 33171868, 2020). "Here, we explore the role of ezrin in macrophage function and interaction with cancer cells primarily using THP-1 monocytic cells as a model system, in conjunction with weakly aggressive MCF-7 and highly aggressive MDA-MB-231 breast cancer cell lines." (PMID 33086476, 2020). "As CD44 promotes breast cancer malignancy by interacting with cytoskeleton linker proteins, such as Ezrin, thus triggering the PI3K-related survival pathway, we next determined the role of Ezrin in CD44/HA induced resistance." (PMID 33024087, 2020). "The ezrin (coded by EZR gene) expression was positive with uniform brown‐yellow granules in the cell membrane, cavity surface and cytoplasm of the cancer cell in breast cancer patients." (PMID 31452341, 2019).
breast carcinoma (continued). "The survival analysis suggested that DCAF13, EZR, MRPL13, APOBEC3C, and EIF4E3 might have a prognostic value for breast cancer." (PMID 30881302, 2019). "Thus, our results open up avenues to the possibility of targeting CCL5 and Ezrin as a strategy to inhibit the effect of MAF on metastasis, predominantly in BRCA1 defective breast cancers." (PMID 30224826, 2018). "Furthermore, it has been reported earlier that hyaluronic acid stimulates the formation of a protein complex consisting of CD44, Hsp90, ErbB2 and ezrin, in TA3/St mammary carcinoma cells." (PMID 27029001, 2016). "Interestingly, ezrin has been found in a molecular complex with CD44, Hsp90 and ErbB2 in mammary carcinoma cells." (PMID 27029001, 2016). "Proteomic analysis of MDA231 CM identified IL-6 as a cytokine regulated by ezrin (data not shown) and the IL-6/Stat3 signaling loop has been reported to promote angiogenesis and metastasis in breast cancer." (PMID 25231728, 2014). "Our identification here of p-ezrin as a crucial molecule in breast cancer dissemination suggests that the roles of NHERF1 and NHE1 in directing metastasis may well be governed by p-ezrin." (PMID 24086451, 2013). "In breast cancer cells, miR-145 suppressed growth and invasion through VEGF and N-Ras, while overexpression of miR-183 resulted in reduced migration and invasion, an effect that was attributed in part to the downregulation of villin 2 (Ezrin)." (PMID 23325049, 2013). "Although the relationship between PTHrP and ezrin has not been extensively studied in breast cancer, similar interactions have been observed in other cancers, such as lung cancer bone metastases, where TGF-β induced both ezrin and PTHrP expression, facilitating tumor growth." (PMID 39827339, 2025). "However, the Multivariate Cox regression analysis showed no significant ezrin expression independence in breast cancer patients’ overall survival." (PMID 39827339, 2025). "Interestingly, the interplay between PTHrP and ezrin in breast cancer has not been previously explored." (PMID 39827339, 2025). "Because of a low number of HER2+ cases within the SEOBC cohort (n = 13), we could not reliably correlate ezrin with this breast cancer subtype." (PMID 36923551, 2022). "It is also unclear if KIF14- and Mieap-positive and EZR-negative cells interact with each other in torpedo-like structures and whether their cooperation is needed for breast cancer invasion and metastasis." (PMID 32679794, 2020). "However, the disease‐free survival (DFS) of breast cancer patients did not correlate with the EZR mRNA level (HR = 0.86, P = 0.44)." (PMID 31452341, 2019). "Induction of cell migration in triple-negative MDA-MB-231 breast cancer cells led to reduced affiliation of CD44 with lipid raft, and this was accompanied by increased association of CD44 with active ezrin, a membrane-cytoskeleton linker, in the nonraft fraction." (PMID 31416894, 2019). "While a couple of UBA6-dependent ubiquitination substrates, i.e., CDC42, ezrin and CUGBP1, are upregulated in cells with UBA6 depletion, it remains to be determined how downregulation of UBA6 activity impact the proteome of mammary epithelial cells during breast cancer development." (PMID 29152096, 2017). "Moreover, three top genes EZR (ranked 12th), TUBB (ranked 27th), and RDX (ranked 36th), were shown to be involved in organization and regulation of morphological characteristics of breast cancer cells including cell shape and membrane to membrane docking." (PMID 28133571, 2017). "However, in breast cancer information on the relationships between ezrin, p-ezrin and clinical-pathological tumor characteristics are lacking." (PMID 24086451, 2013). "Therefore, the role of ezrin in sex steroids-sensitive breast cancer metastasis should not be neglected." (PMID 21818323, 2011).
breast carcinoma (continued). "Also in contrast to published studies with osteosarcoma and breast cancer cells, we detected no involvement of the linker protein ezrin in the phenotype that ICAM-2 conferred on neuroblastoma cells." (PMID 18978946, 2008). "In addition, interaction of ezrin with other signalling molecules such as the Na+/H+ exchanger regulatory factor (NHERF-1), recently described to be altered in breast cancer, may also be involved." (PMID 15987432, 2005). "In addition, research in vitro is required to confirm whether positive expression of KIF14 and Mieap, as well as negative expression of EZR, are critical for breast cancer migration and invasion." (PMID 32679794, 2020). "Interestingly, expression of KLK5 was high in basal-like and normal-like breast cancer subtypes with a reduction in levels in luminal B. There was reduced expression in normal tissue and basal subtypes with higher expression in luminal (ER+) and Her-2 subtypes for ITGB5, EZR, COL12A1, and COL24A1." (PMID 25593998, 2014). "However, the role played by ezrin in breast cancer metastasis has not been clearly delineated." (PMID 15987432, 2005). "However, the role played by ezrin in breast cancer metastasis has not been delineated." (PMID 15987432, 2005). "While we could not evaluate whether ezrin levels are upregulated in acquired chemotherapeutic drug-resistant breast cancer cell lines in our study, we showed that altering ezrin levels can change the sensitivity of breast cancer cells to DOX and DTX treatment in vitro." (PMID 36923551, 2022). "This closely matches the values for total ezrin, but not total radixin, supporting the conclusion that ezrin expression and activation state correlates with NSC sensitivity in this panel of breast cancer cell lines." (PMID 36923551, 2022). "Using a highly metastatic mouse mammary carcinoma cell line (AC2M2), we tested the effect of over-expressing a non-phosphorylatable form of ezrin (Y477F) on invasive colony growth in 3-dimensional Matrigel cultures, and on local invasion and metastasis in an orthotopic engraftment model." (PMID 22397367, 2012).
osteosarcoma (85 papers, 2003 to 2026). A usually aggressive malignant bone-forming mesenchymal neoplasm, predominantly affecting adolescents and young adults. "This has also been observed in osteosarcoma, where circulating tumor cells with higher Ezrin expression are associated with distant metastasis." (PMID 37371090, 2023). "Ezrin, a protein reported closely associated with osteosarcoma metastasis, was confirmed to be an interactive protein for PARP1." (PMID 35173550, 2022). "In osteosarcoma, ezrin expression has been associated with lung metastasis in vivo, and inhibition of ezrin reduces the metastasis." (PMID 36077137, 2022). "In other studies, it is well-known that the expression levels of KI67 and EZRIN are associated with metastasis and chemotherapy responses in pediatric osteosarcoma." (PMID 34071614, 2021). "Ezrin is required for metastasis in osteosarcoma and its high expression is associated with poor outcomes in pediatric osteosarcoma patients." (PMID 33240887, 2020). "Ezrin, a cytoskeleton linker protein involved in regulation of growth, has been associated with metastatic potential and poor prognosis in mouse models of osteosarcoma." (PMID 32039013, 2019). "In osteosarcoma mouse models, ezrin was associated with increased metastatic potential and poorer prognosis while high ezrin expression correlated with chemotherapy resistance." (PMID 32039013, 2019). "It has been reported that high ezrin expression was associated with metastasis and poor outcome in pediatric patients with osteosarcoma." (PMID 29899165, 2018). "Some markers reported to be associated with aggressive osteosarcomas are β4 Integrin, Ezrin, and Cullin-1." (PMID 30576337, 2018). "Preclinical studies demonstrated that sirolimus, the main mTOR inhibitor, blocks the ezrin pathway implicated in the metastatic migration of osteosarcomas." (PMID 26541413, 2015). "This meta-analysis showed that ezrin immunoexpression had an unfavorable impact on overall survival and was associated with recurrence in patients with osteosarcoma." (PMID 23805177, 2013). "The results of this meta-analysis suggest that ezrin positive immunoexpression confers a higher risk of recurrence and a worse survival in osteosarcoma patients." (PMID 23805177, 2013). "This meta-analysis suggests that ezrin was seems to be associated with a worse prognosis for OS and recurrence of patients with osteosarcoma with available evidence." (PMID 23805177, 2013). "The first research that identified an association between ezrin expression and outcome in osteosarcoma was published in 2004." (PMID 23805177, 2013). "The combined HR was 4.79 (95% CI: 1.50–15.30; Z = 2.64; P = 0.008), which demonstrated that ezrin immunoexpression was significantly associated with the poor OS of osteosarcoma patients." (PMID 23805177, 2013). "We found that ezrin mmunoexpression had an unfavorable impact on osteosarcoma patients' overall survival and was associated with recurrence." (PMID 23805177, 2013). "Increased ezrin expression in paediatric osteosarcoma patients is associated with reduced disease-free intervals, and downregulation of ezrin expression in a mouse model of human osteosarcoma has been shown to reduce pulmonary metastasis." (PMID 21559216, 2011). "Supporting this, pRb-deficient osteoblasts expressed elevated levels of ezrin, a membrane-cytoskeleton linker whose up-regulation is considered an indicator of osteosarcoma metastasis." (PMID 21085651, 2010). "However, studies with osteosarcoma as well as skin melanoma cell lines and uveal melanoma have shown an association between high Ezrin expression and poor clinical outcome." (PMID 36142656, 2022). "High ezrin expression has been linked to a poor prognosis in osteosarcoma." (PMID 36077137, 2022). "Ezrin was suggested to be involved in the metastasis of osteosarcoma 43, 44, and the underlying molecular mechanism involved in the modulation of metastasis by ezrin might be different in different cancers." (PMID 31376222, 2019).